ALKBH3 (alkB homolog 3, alpha-ketoglutarate dependent dioxygenase)
Diseases named in the same sentence as ALKBH3 in open-access papers (continued):
Sharing a sentence is not in itself a finding about the gene and the disease.
metastatic melanoma (1 paper, 2024). A melanoma that has spread from its primary site to another anatomic site. "Consistently, ALKBH3 exhibited a significant negative correlation with SP100 in a group of 87 metastatic melanoma samples (deposited in GEO database: GSE7553, R = –0.227, P= 0.035)." (PMID 38118002, 2024).
non-small cell lung adenocarcinoma (1 paper, 2015). Type of epithelial lung cancer arising from glandular origin. "ALKBH3 knockdown also causes an upregulation of inflammatory genes in the non-small cell lung adenocarcinoma cell line NCI-H23, suggesting that ablation of ALKBH3-dependent DNA repair mechanisms induces inflammatory pathways in multiple cancer cell lines." (PMID 26221185, 2015).
pulmonary diseases (1 paper, 2024). "Alkbh3-mediated m1A modification is involved in multiple diseases related to carcinogenesis, nervous system diseases, cardiovascular diseases and pulmonary diseases." (PMID 39004750, 2024).
small cell carcinoma (1 paper, 2011). A neuroendocrine carcinoma composed of small malignant cells which are often said to resemble "oat cells" under the microscope. "Immunohistochemical results showed that ALKBH3 was highly expressed in 75% of both adenocarcinoma and squamous cell carcinoma samples, but expressed to a lesser degree in only 25% of small-cell carcinomas." (PMID 21285982, 2011).
small cell lung carcinoma (1 paper, 2011). Small cell lung cancer (SCLC) is a highly aggressive malignant neoplasm, accounting for 10-15% of lung cancer cases, characterized byrapid growth, and early metastasis. "Before we began the larger study, we initially performed a limited survey of the expression profile of ALKBH3 using four samples each of small-cell lung cancer, adenocarcinoma and squamous cell carcinoma." (PMID 21285982, 2011).
squamous cell tumours (1 paper, 2011). "Of those specimens, 50% of adenocarcinomas and 56.5% of squamous cell tumours demonstrated ⩾30% of cells immunopositive for ALKBH3." (PMID 21285982, 2011).
thyroid cancer (1 paper, 2025).
cancer (53 papers, 2011 to 2025). A tumor composed of atypical neoplastic, often pleomorphic cells that invade other tissues. "In contrast, ALKBH3 promotes cancer cell invasion through m1A demethylation, causing tRNA destabilization." (PMID 38304034, 2023). "We originally detected ALKBH3 expression in the prostate, and were able to demonstrate that a number of molecules associated with ALKBH3 were involved in cancer metastasis or resistance to anticancer drugs." (PMID 21285982, 2011). "Among them, ALKBH3 shows a significant association with PD-L1 in various types of cancer." (PMID 37628671, 2023). "ALKBH3 is an intrinsic DNA repair protein that suppresses transcription-associated DNA damage at highly-expressed genes and thereby plays a role in maintaining genomic integrity in ALKBH3-overexpressing cancer cells." (PMID 26703582, 2015). "Further, we propose that ALKBH3 is an intrinsic DNA repair protein that suppresses transcription associated DNA damage at highly expressed genes and thereby plays a role to maintain genomic integrity in ALKBH3-overexpressing cancer cells." (PMID 26221185, 2015). "Moreover, ALKBH3 overexpression is significantly linked to poor prognosis in cancer patients." (PMID 28205560, 2017). "Overall, ALKBH3 plays an oncogenic role in multiple cancers, mainly by regulating the stability and translation of certain key mRNAs." (PMID 40483535, 2025). "In the tumor context, the demethylase ALKBH3 promotes cancer progression by demethylating tRNA, which enhances its cleavage into tRNA-derived small RNAs (tDRs)." (PMID 41446042, 2025). "Beyond m6A, emerging evidence identifies ALKBH3 as a demethylase for m1A and m3C in tRNAs, influencing cellular stress responses; its role in cancer immunity remains to be fully elucidated but represents a promising frontier." (PMID 41280938, 2025). "In various cell lines, ALKBH3 can promote the proliferation of cancer cells via demethylating tRNAs and generating tRNA-derived small RNAs." (PMID 40483535, 2025). "In this study, we revealed that histone lactylation is also responsible for the oncogenic activation of the ALKBH3, contributing to the hypo-m1A status in cancers." (PMID 38118002, 2024). "Again, selective upregulation of transcriptional and epigenetic regulators in responders is evident; examples include PRDM5, ZNF230, ZCCHC9, ZKSCAN4, and the epigenetic regulator ALKBH3, which demethylates DNA and RNA in cancer cells." (PMID 39450169, 2024). "In most cancer subtypes, the m1A demethylase ALKBH3 plays an oncogenic role in the development of cancer through various regulatory mechanisms." (PMID 39160604, 2024). "For example, ALKBH3-mediated tRNA demethylation efficiently promotes cancer progression via induction of tRNA-derived small RNAs, which prevents apoptosis induced by cytochrome C." (PMID 38118002, 2024). "Through modifying the expression of m1A-methylated ATP synthase F1 subunit delta (ATP5D) mRNA, ALKBH3 stimulates the glycolysis of cancer cells." (PMID 39459530, 2024). "High levels of ALKBH3 in cancer cells decrease the abundance of m1A and m3C on tRNAs and promote cancer progression by facilitating the biogenesis of tsRNAs." (PMID 39456272, 2024). "ALKBH3 promoted cancer cell proliferation, migration and invasion by demethylating tRNAs, generating tRNA-derived small RNAs (tDRs) that prevent Cytochrome C-triggered apoptosis in various cancer cell lines." (PMID 37612540, 2023). "Later research revealed that ALKBH3 plays crucial roles in cancer cell proliferation as well as metastasis." (PMID 37612540, 2023). "ALKBH3 inhibitors also effectively inhibit the development and invasive ability of cancer cells implanted in vivo." (PMID 37007161, 2023). "Like ALKBH1, ALKBH3, as enzymes that can bind to tRNA and affect cancer prognosis by regulating protein synthesis, is also a new research direction." (PMID 37007161, 2023).
cancer (continued). "The tRNAs with m1A and m3C demethylated by ALKBH3 can produce tRNA-derived small RNAs (tDRs), thereby promoting cancer development." (PMID 37007161, 2023). "The knockdown of ALKBH3 can downregulate expression of VEGF to inhibit the cancer angiogenesis in vivo experiment." (PMID 35937999, 2022). "The produced tDRs are engaged in ALKBH3-mediated cancer progression via modulating ribosome assembly and preventing apoptosis pathway triggered by cytochrome c (Cyt c)." (PMID 34272618, 2021). "Our recent study indicated that tRNA demethylase AlkB Homolog 3 (ALKBH3) can promote cancer progression via induction of tDRs." (PMID 33563322, 2021). "On the other hand, ALKBH3 is often overexpressed in different cancers and inhibition of ALKBH2 and ALKBH3 can sensitize cancer cells to alkylating chemotherapy." (PMID 34723799, 2021). "The role of tDRs including 5′-tRF-GlyGCC in the promotion effects of ALKBH3 on cancer progression needs further study." (PMID 33563322, 2021). "In diverse cancer subtypes, ALKBH3 functions as an m1A demethylase and plays an oncogenic role in cancer progression via various regulatory mechanisms." (PMID 34272618, 2021). "ALKBH3 is reported to be highly expressed in a number of human cancers; knockdown of ALKBH3 increased m1A levels in tRNA and decreased protein synthesis in cancer cells." (PMID 34638642, 2021). "It is noteworthy that ALKBH3 was recently reported to be a tRNA demethylase for promoting the protein-synthesizing process in cancer cells." (PMID 34188972, 2021). "Available evidences also indicate that several members of AlkB family, such as ALKBH3 and ALKBH5, are closely linked to the inhibition of tumorigenesis and progression in various human cancers." (PMID 32478065, 2020). "In this context, ALKBH3 overexpression likely relates to adaptation of cancer cells to tolerate endogenous alkylation damage to DNA or RNA." (PMID 28679371, 2017). "An activating signal co-integrator complex subunit 3 (ASCC3) is a DNA helicase and unwinding by ASCC3 is coupled with ALKBH3-dependent DNA alkylation repair and cancer cell proliferation in mammalian cells." (PMID 28757607, 2017). "To examine ALKBH3’s role in cancer we preferentially used data from prostate (for example, LNCaP) or other human cancer cell lines." (PMID 26221185, 2015). "At 7 and 14 days after intraperitoneal injection of cancer cells, control siRNA or ALKBH3 siRNA was intraperitoneally injected in the presence of atelocollagen as described in Materials and Methods." (PMID 21285982, 2011). "ALKBH3, currently the only known m1A demethylase for mRNA, recognizes and removes m1A and N3-methylcytosine (m3C) modifications, and has been shown to regulate cancer cell glycolysis in a demethylation activity-dependent manner." (PMID 41446042, 2025). "Recent progress has revealed ALKBH3’s function as a cancer-promoting factor in various cancers." (PMID 40675967, 2025). "Notably, the increased expression of the m1A demethylase ALKBH3 is frequently observed in many cancers and accelerates malignant proliferation and invasion." (PMID 38118002, 2024). "Additionally, ALKBH3 promotes cancer proliferation, migration, and invasion by inducing tDRs and strengthening ribosome assembly, thereby facilitating cancer progression." (PMID 38943267, 2024). "The role of ALKBH3 in cancer is characterised by a striking dichotomy." (PMID 38672281, 2024). "Therefore, ALKBH3 can accelerate cancer progression by promoting cancer cell proliferation and invasion." (PMID 39247598, 2024). "In addition, tRNAs with m1A, m3C, and m6A demethylated by ALKBH3 in cancer cells increase the efficiency of protein synthesis." (PMID 37007161, 2023).
cancer (continued). "ALKBH3 could positively regulate the glycolysis of cancer cells by demethylating an important adenosine 5’-triphosphate synthase subunit, ATP5D, whose m1A modification negatively regulated its own translation elongation and mRNA release from ribosome complex." (PMID 37612540, 2023). "Also, the overexpressed ALKBH3 is observed in a few human cancers, and its expression is correlated with the TNM stage, such as pancreatic cancer." (PMID 35937999, 2022). "Of note, ALKBH3 can demethylate m1A tRNA to promote protein synthesis, which may contribute to the cancer development." (PMID 35937999, 2022). "In addition, ALKBH3 is highly expressed in various cancers to trigger the cancer progression via induction of tDRs." (PMID 33563322, 2021). "The functional interplay of ASCC and AlkBH3 in DNA de-alkylation repair may thus also have repercussions for cancer chemotherapy." (PMID 33139697, 2020). "On the other hand, the high amount of the repair protein ALKBH3 present in larger tumours may be explained by accumulation of alkylation damage to DNA/RNA, due to metabolic instability of the developed cancer." (PMID 31519943, 2019). "In addition, ALKBH3 knockdown in human cancer cells impaired cellular proliferation and suppressed the nascent protein synthesis that is usually accompanied by accumulation of the methylated RNAs." (PMID 28205560, 2017). "Therefore, highly expressed ALKBH3 would maintain genome integrity through these regulation mechanisms in actively proliferating cancer cells." (PMID 28205560, 2017). "The over-expression of ALKBH3 in cancer cells might facilitate alkylation damage resistance during cancer treatment and therefore raises the possibility of ALKBH3 as a potential anticancer target in the future." (PMID 26221185, 2015). "Previous work suggested a pivotal role of ALKBH3 in multiple cancer types, such as prostate, pancreatic, urothelial, non-small-cell lung, papillary thyroid, and brain cancer." (PMID 26221185, 2015). "Enzymes that facilitate DNA alkylation damage repair, such as ALKBH2 and ALKBH3, can contribute to resistance to this treatment and insights into their molecular function could provide the basis for developing more efficient cancer therapies." (PMID 26221185, 2015). "ALKBH3 upregulation in cancer could be an important step during cancerogenesis to achieve an increased proliferation rate while maintaining genomic integrity." (PMID 26221185, 2015). "However, EGFR and ras mutations are not a common feature of many tumours; our data strongly suggest that ALKBH3 would be an important marker and target in a wide range of cancers." (PMID 21285982, 2011). "It is unknown whether ALKBH3 can function as a substrate for PUS7 in other cancer types." (PMID 39175405, 2024). "Moreover, their investigation revealed the ubiquitous expression of ALKBH3 in cancer cells, where it can act as a catalyst for cancer progression, generating tRNA fragment (tDRs) that facilitate ribosome assembly while inhibiting apoptosis in cancer cells." (PMID 38291517, 2024). "Moreover, elevated ALKBH3 expression is found in several cancers, including BLCA." (PMID 38304034, 2023). "It is currently unknown whether ALKBH2 or ALKBH3 undergo epigenetic silencing in cancer." (PMID 28679371, 2017). "Since ALKBH3 has a substrate preference for RNA as well as ssDNA, the defective repair of RNA methylation damage induced by endogenous and exogenous methylating agents may contribute to cancer progression." (PMID 28205560, 2017). "If true, this would suggest that ALKBH3 inhibition could potentially slow cancer progression." (PMID 26221185, 2015). "The presence and percentage of ALKBH3-positive cells might offer a meaningful way to predict/detect cancer recurrence at an earlier stage; moreover, targeting therapy to the ALKBH3 gene might markedly improve the clinical outcome for patients with adenocarcinoma." (PMID 21285982, 2011).
cancer (continued). "While the mechanisms of ALKBH3 ubiquitination in GBM still require characterisation, it is not excluded that a similar phenomenon occurs in this type of cancer as well." (PMID 38672281, 2024). "The proliferation of cancer cells has been found to be promoted by m1A regulators, such as TRMT6, TRMT61A, and ALKBH3, in colorectal cancer, gastric cancer, glioma, hepatocellular cancer (HCC), and prostate cancer." (PMID 39459530, 2024). "The expression of m1A regulators has previously been investigated in various cancers, and upregulation of TRMT6, TRMT61A, and ALKBH3 has been reported in BLCA." (PMID 38304034, 2023). "ALKBH3 and prostate cancer antigen-1 (PCA-1) are identical and abundantly expressed in many human cancers." (PMID 37007161, 2023). "ALKBH3 (p < 0.001), TRMT61A (p < 0.001), YTHDF1 (p < 0.001), ALKBH1 (p < 0.001), and TRMT6 (p < 0.001) in cancer tissues were significantly up-regulated compared to those in normal tissues (p < 0.001)." (PMID 34195072, 2021). "In the cancer tissue, we observed a similar correlation involving ALKBH5-FTO, ALKBH3-ALKBH5, and ALKBH1-ALKBH5, but also noted that the level of ALKBH2 was correlated with that of ALKBH5 and ALKBH1 with ALKBH3." (PMID 31519943, 2019). "However, it is currently unknown whether ALKBH2 or ALKBH3 are found inactivated in cancer." (PMID 28679371, 2017). "Recently, we described the cooperativity of ALKBH3 and the ASCC3 DNA helicase complex to promote DNA alkylation damage repair in various cancer cells." (PMID 26221185, 2015). "To evaluate its function in ATC drug resistance, we examined correlations between the expression of 12 m5C regulators [NSUN2-7, TRDMT1 (writers); ALKBH1, TET2, ALKBH3 (erasers); YBX1 and ALYREF (readers)] and drug sensitivity in the Cancer Therapeutics Response Portal (CTRP)." (PMID 40083919, 2025). "In this study, we revealed for the first time that ALKBH3-mediated m1A modification plays an inhibitory role in the formation of the PML body, which bridges our understanding of dynamic RNA modifications and phase-separation events in cancers." (PMID 38118002, 2024). "For instance, ALKBH3 can demethylate the m1A on tRNA, making tRNA more sensitive to angiogenin (ANG) cleavage, thereby generating tRNA‐derived small RNAs (tDRs) around the anticodon regions and promoting cancer cell proliferation, migration and invasion." (PMID 39175405, 2024). "Furthermore, inhibition of Alkbh3, an m1A demethylase, resulted in decreased proliferation in HeLa, PANC-1, and NSCLC cancer cells, suggesting a potential role for this demethylase in proliferation." (PMID 35350378, 2022). "That downregulation of ALKBH3 sensitized cancer cells but not normal cells to alkylating agents suggested that this dependency on ALKBH3 is cancer‐specific." (PMID 34561912, 2021). "Indeed, ASCC3 is overexpressed in several cancers and ASCC3 knockdown, which would be expected to lead to less efficient AlkBH3-mediated DNA de-alkylation repair, has been shown to negatively impact tumor cell proliferation in culture and xenograft models." (PMID 33139697, 2020). "In this study, we evaluated the role of ALKBH3 in cancer cell survival, but not in the sensitivity to anticancer drugs including alkylating reagents." (PMID 21285982, 2011). "In breast and ovarian cancers, ALKBH3 induces the abundance of m1A-modified colony-stimulating factor 1 (CSF1) mRNA, which enhances its translation initiation and cancer cell invasiveness, while it can also promote cancer cell invasion through destabilization of tRNAs." (PMID 39459530, 2024). "Currently, there is no consensus regarding the role of ALKBH3 in cancer." (PMID 38672281, 2024). "Herein, we found that histone lactylation enhances ALKBH3 expression and simultaneously attenuates the formation of tumor-suppressive promyelocytic leukemia protein (PML) condensates by removing the m1A methylation of SP100A, promoting the malignant transformation of cancers." (PMID 38118002, 2024).
cancer (continued). "So far, the roles of ALKBH1, ALKBH2, and ALKBH3 in cancer regulation have not been studied much." (PMID 37007161, 2023). "For example, ALKBH3 is important for the repair of DNA alkylation damage, indicating a possibility that ALKBH3 function in cancer may be independent of its catalytic activity as m1A demethylase." (PMID 37612540, 2023). "Similarly, we found no further increase in γH2AX upon glutamine starvation in ALKBH3 knockdown PC3 cancer cells." (PMID 29107960, 2017).